PCNA (proliferating cell nuclear antigen)
Diseases named in the same sentence as PCNA in open-access papers (continued):
Sharing a sentence is not in itself a finding about the gene and the disease.
Fanconi anemia (21 papers, 2011 to 2026). Fanconi anemia (FA) is a hereditary DNA repair disorder characterized by progressive pancytopenia with bone marrow failure, variable congenital malformations and predisposition to develop hematological or solid tumors. "The actions of UL138 are due, in part, to its modulation of pathways regulated by the cellular deubiquitinating complex that targets proliferating cell nuclear antigen (PCNA) and Fanconi Anemia effectors, FANCD2 and FANCI." (PMID 41533576, 2026). "As a DUB, USP1 regulates several factors of DDR, especially proliferating cell nuclear antigen and Fanconi anemia group D2 protein, which plays an important role in translesion synthesis and Fanconi anemia pathway." (PMID 39814232, 2025). "USP1 plays an important role in DNA damage response (DDR) by deubiquitinating proliferating cell nuclear antigen and Fanconi anemia group D2 protein." (PMID 39814232, 2025). "Well-characterized substrates of USP1 include FANCD2 and FANCI, key components of the Fanconi anemia DNA repair pathway, as well as PCNA, which plays a central role in DNA replication and repair." (PMID 40940964, 2025). "USP1 also plays a critical role in DNA repair by deubiquitinating key proteins such as FANCD2 and PCNA, thereby regulating the Fanconi anemia pathway and homologous recombination." (PMID 40940964, 2025). "Currently, several proteins are deubiquitinated and stabilized by USP1, and this process facilitates cancer progression, including Fanconi anemia group D2 protein and proliferating cell nuclear antigen, which are known to be involved in the DNA damage response pathway." (PMID 39513905, 2024). "Importantly, Pol kappa-mediated DNA synthesis during hydroxyurea (HU)-dependent fork restart is regulated by both the Fanconi Anemia (FA) pathway and PCNA polyubiquitination." (PMID 30422114, 2018). "Finally, USP1 deubiquitinates and inactivates two components of DNA repair mechanisms: FANCD2 (a component of the Fanconi Anemia pathway) and PCNA." (PMID 21283576, 2011). "Moreover, PCNA ubiquitination is important during somatic hypermutation of immunoglobulin genes in B cells and plays a role in haematopoiesis, independently of a previously discovered function in activation of the Fanconi anaemia pathway." (PMID 38528023, 2024). "As a member of USPs, USP1 plays important role in DNA repair through deubiquitinating Fanconi anemia complementation group I (FANCI), Fanconi anemia group D2 (FANCD2), and proliferating cell nuclear antigen (PCNA)." (PMID 34873426, 2021). "This response articulates itself on three important platforms, Replication Protein A/RPA-coated single-stranded DNA, the DNA polymerase processivity clamp PCNA and the FANCD2/I Fanconi Anemia complex." (PMID 30257459, 2018). "For instance, upon DNA damage, the Fanconi Anemia protein FANCD2 is mono-ubiquitinated and re-localizes to the chromatin whereas ubiquitin-modified proliferating cell nuclear antigen (PCNA) recruits a specific DNA polymerase." (PMID 22347420, 2012). "By promoting the monoubiquitination of proliferating cell nuclear antigen (PCNA), RAD18 activates the Fanconi anemia (FA) pathway and recruits TLS polymerases such as DNA polymerase η (pol η) and DNA polymerase ι (pol ι), enabling cancer cells to continue DNA synthesis in damaged genomes." (PMID 39905312, 2025). "In contrast, two different groups recently showed that the ubiquitin ligase activity of RAD18 is required for Fanconi Anemia pathway activation at DSBs, independent of PCNA ubiquitylation." (PMID 21858012, 2011).
liver cancer (21 papers, 2002 to 2025). An epithelial or non-epithelial malignant neoplasm that arises from the liver. "In liver cancer patients, high proliferating cell nuclear antigen (PCNA) expression is associated with increased involvement of blood vessels, and reduced postoperative disease-free survival time." (PMID 27153056, 2016). "MCM6, CDC20, and PCNA are also associated with prognosis in liver cancer." (PMID 32082966, 2019). "Compared to normal liver tissue, the mRNA levels of XRCC1, MAPK3, and PCNA were significantly elevated in liver cancer tissue." (PMID 39346898, 2024). "We observed accelerated apoptosis and decreased PCNA expression after the CFT‐1 treatment in liver cancer cells via immunohistochemistry and TUNEL assay, which is consistent with former studies." (PMID 31428352, 2019). "Clinically, the expression levels of PCNA were remarkably elevated in HBV cccDNA-positive liver cancer tissues." (PMID 31410212, 2019). "Interestingly, PCNA LI in liver tissue taken from the resected lobes of malignant liver tumor patients was significantly higher than in liver of benign lesion patients." (PMID 14960204, 2004). "The findings suggest that the transfected p21WAF1/CIP1 likely has no apparent effect on the expression of cdks but may block the ability of PCNA to activate DNA polymerase δ and the cdk kinase activity in human liver cancer cells." (PMID 11870547, 2002). "GTSE1, together with CDC20, PCNA, and MCM, presented unfavorable prognosis of liver cancer in our study." (PMID 32082966, 2019). "This suggests that in the pathogenesis of liver cancer, TM4SF1 upregulates cyclin D1 and PCNA and thereby promotes the growth, proliferation, and invasion of cancer cells." (PMID 27153056, 2016). "Our results indicate HOTAIR causes microsatellite instability (MSI) and abnormral expression of cell cycle related gene, e.g. CDK2, CyclinE, CDK4, CyclinD1, PCNA, ppRB, E2F1 in liver cancer stem cells." (PMID 26172293, 2015). "Within liver cancer (SMMC-7721) cells, ginsenoside Rg3 potentiates oxaliplatin's anti-cancer properties, curbing liver cancer growth and facilitating cell death through the control of PCNA and Cyclin D1 expression." (PMID 40490812, 2025). "Furthermore, increased CBX7 greatly reduced tumour proliferation as measured by PCNA, and one CBX7 target, cyclin E1, which is essential for liver cancer progression, was significantly reduced upon increased CBX7 expression." (PMID 35867177, 2022). "Genes like GTSE1, CDC20, PCNA, and MCM6 may be promising prognostic molecular biomarkers in liver cancer." (PMID 32082966, 2019). "Among the DEGs, CDC20, PCNA, and MCM6 might synergistically affect regulations in cell cycle with GTSE1 and might be potential prognostic predictors in liver cancer." (PMID 32082966, 2019). "Additionally, the knockdown of PCNAP1 dose-dependently decreased the expression levels of PCNA in HepG2.2.15 and PLC/PRF/5 cells, indicating that PCNAP1 is able to up-regulate PCNA in liver cancer." (PMID 31410212, 2019). "During induction of liver cancer using the MRHM, the proliferation of hepatocytes increases; therefore, we tested whether 4.5 mT - 120 Hz ELF-EMF exposure affects the expression of PCNA, Ki-67 and cyclin D1." (PMID 20416104, 2010). "Propofol can reduce the expression of PCNA, CD34, and PATK proteins in patients, thereby increasing the activity and content of transforming growth factor TGF-β1 by 12% and 20%, respectively, thereby inhibiting the proliferation rate of liver cancer cells by 10% through the Smad2 signaling pathway." (PMID 34323647, 2021). "However, HULC plus PTEN did significantly not alter the PCNA positive rate of liver cancer cells (40.97 ± 9.34%versus 31.83 ± 6.41%, P = 0.1397 > 0.05)." (PMID 29895332, 2018). "However, MEG3 plus β-catenin did not significantly alter the PCNA positive rate of liver cancer cells (49.13 ± 12.38% versus 41.33 ± 7.88%, P = 0.237289 >0.05)." (PMID 29449541, 2018).
neuroblastoma (20 papers, 2007 to 2025). Neuroblastoma (NB) is the most common solid, extracranial childhood tumor. "Cytoplasmic PCNA is also associated with Caspase-9 in the SH-SY5Y neuroblastoma cell line, and S-nitrosylation of PCNA at the residues C81 and C162 decreases this interaction, leading to caspase-9 activation." (PMID 35677658, 2022). "Recently, a few studies have demonstrated the cytoplasmic localization of PCNA and its function associated with apoptosis in neutrophil and neuroblastoma cells." (PMID 32597793, 2020). "Moreover, in human neuroblastoma cells, the association between procaspase-9 and cytosolic PCNA could be disrupted after S-nitrosylation of PCNA, in turn triggering apoptosis." (PMID 27759041, 2016). "We further showed that CDKN3 knockdown reduced expression of cell proliferation markers Ki67 and proliferating cell nuclear antigen (PCNA), and reduced colony formation of neuroblastoma cells." (PMID 38356706, 2024). "Immunohistochemical staining (IHC) results showed that neuroblastoma tissues treated with luteoloside had low expression of PCNA and Ki67." (PMID 36838737, 2023). "SH-SY5Y neuroblastoma cells express proliferative markers such as the immature neuronal marker nestin and the Proliferating cell nuclear antigen (PCNA)." (PMID 34557995, 2022). "Combination drug treatment with SAHA and SE486-11 reduced MYCN, USP5 and PCNA (proliferation marker) protein levels in neuroblastoma-bearing MYCN;GFP zebrafish compared to DMSO treated controls." (PMID 33658627, 2021). "Ki67 and PCNA, which are typical indicators of neuroblastoma proliferation, were also significantly reduced." (PMID 34384466, 2021). "We then re-ran the MR analysis within the two neuroblastoma networks using as query the meta-PCNA proliferative gene signature." (PMID 24349289, 2013). "The histological analysis of these tissues, together with the PCNA immunohistochemistry data, were however suggestive of a forthcoming regression, or at least growth arrest, of neuroblastomas expressing HIF2α DN." (PMID 17655754, 2007). "The most prominent predicted target of the LSEC-LSEC communication was proliferating cell nuclear antigen (PCNA) clamp-associated factor (Pclaf), which has been associated with cell cycle progression in multiple tumors, including neuroblastoma, through its interaction with PCNA64,65." (PMID 40603966, 2025). "PCNA expression is known to be correlated with the proliferative activity in neuroblastomas." (PMID 23292364, 2013). "We found that neuroblastomas arising in the nf1a+/- and nf1a-/- background exhibited a progressively higher percentage of nuclei with PCNA staining (30% for nf1a+/- and 80% for nf1a-/-) compared to PCNA staining of 20% of nuclei in the wild-type nf1a+/+ genotype." (PMID 27130733, 2016). "MJ impaired the G2-to-M transition in the human neuroblastoma SH-SY5Y cells, downregulating the expressions of the proliferating cell nuclear antigen (PCNA, a processivity factor encircling DNA at sites of replication and repair) and N-Myc." (PMID 24648844, 2014). "Furthermore, in APPswe Tg mice, proliferation markers, such as PCNA, seem to induce cell cycle re-entry and its mRNA levels have been found to be increased in brain tissue from AD patients and in APP human neuroblastoma SH-SY5Y cells." (PMID 34440085, 2021). "We show that treatment of mouse neuroblastoma Neuro-2A cells with Tet34, but not its scrambled control (Tet34s), induced cell proliferation, as manifested by changes in protein levels of transcription factors and progrowth molecules cyclin D1, PCNA, Sox5, and Cdk2." (PMID 36162508, 2022).
endometriosis (19 papers, 2005 to 2025). The growth of functional endometrial tissue in anatomic sites outside the uterine body. "Decreased size of endometriosis lesions is associated with decreased PCNA levels, and PCNA levels are directly related to the size of endometriosis lesions." (PMID 36381357, 2022). "Resveratrol treatment lowers the quantity of PCNA + and Ki-67 + endometrial cells in the rat model of peritoneal and mesenteric endometriosis, which slows the growth rate of endometriotic implants in comparison to the control group." (PMID 41233892, 2025). "Many papers have shown the importance of cell proliferation during endometriosis, evaluating the expression of Ki-67 and PCNA proteins." (PMID 34206129, 2021). "Assessment of the RNA interaction network in endometriosis has resulted to identification of the role of miRNAs and lncRNAs that are associated with cyclin-dependent kinase 1 (CDK1) and proliferating cell nuclear antigen (PCNA)." (PMID 32850438, 2020). "Adipose tissue harvested from endometriosis patients showed alterations in cell proliferation corresponding to decreased nuclear PCNA expression." (PMID 30982470, 2019). "We identified a shift to cytosolic PCNA in endometriosis that likely also increases glycolysis, thus altering availability of lipid precursors." (PMID 30982470, 2019). "Compared with the untreated endometriosis mice, treatment with nobiletin significantly lowered PCNA and VEGF immunostaining, and showed higher staining level of E-cadherin in both low- and high-dose of nobiletin treated groups (P<0.01)." (PMID 29871974, 2018). "In order to confirm these results, we assessed the expression of PCNA, a marker of cell proliferation, in the different combination of endometriosis-like lesions." (PMID 25329068, 2014). "PCNA expression levels are known to be elevated in endometrial hyperplasia and endometriosis." (PMID 36381357, 2022). "The findings of this study suggest that DNG may reduce cell viability and proliferation in response to treatment with estrogen, TNF-α, IL-1β, or IL-32, and inhibit the pathogenesis of endometriosis by decreasing PCNA expression." (PMID 36428561, 2022). "Evaluation of the RNA interaction network in endometriosis has revealed the role of miRNAs and lncRNAs associated with growth and apoptosis genes regulation in endometrial stromal cells, namely, Cyclin-Dependent Kinase 1 (CDK1) and Proliferating Cell Nuclear Antigen (PCNA)." (PMID 40792071, 2025). "In animal models of endometriosis, knockdown of NF-κB expression significantly reduced PCNA production and microvessel density in ectopic lesions, suggesting that NF-κB could be considered as a therapeutic target for preventing ectopic lesion growth and angiogenesis." (PMID 37143676, 2023). "Thus, DNG may reduce cell viability and proliferation induced by estradiol, TNF-α, IL-1β, and IL-32, and inhibit the endometriosis pathogenesis by decreasing PCNA expression." (PMID 36428561, 2022). "An animal study revealed naringenin potential against endometriosis by reducing expression of various endometriosis prognostic markers (TAK1, PAK1, VEGF, PCNA, MMP2, and MMP-9) in endometriotic lesions developed in rats." (PMID 33919512, 2021). "Immunostaining results showed weaker nuclear PCNA and increased cytoplasmic staining in fat tissue of endometriosis patients compared to non-endometriosis patients." (PMID 30982470, 2019). "While the majority of staining was nuclear in adipocytes cultured from women without endometriosis, the majority of PCNA was cytoplasmic in cells from endometriosis patients." (PMID 30982470, 2019). "To gain further insight into the adipocyte cell proliferation and metabolism in subcutaneous fat from patients with and without endometriosis, we assessed the cultured adipocytes for expression of PCNA, a marker of cell proliferation, and for vimentin and DAPI simultaneously." (PMID 30982470, 2019).
viral infection (19 papers, 2008 to 2026). "The goal of this study was to determine what role PCNA associated with HSV-1 replication forks plays during viral infection." (PMID 37486931, 2023). "Proteins, including cofilin and MARCKS, proliferation marker PCNA, and the energy “linked” protein, pyruvate kinase, were down-regulated after viral infection, whereas calmodulin was up-regulated." (PMID 18575609, 2008). "Together with the findings that PCNA selectively associates with viral replication forks and that PCNA knockdown by transfected siRNAs results in reduced viral infection, data presented here provide additional support for a role of PCNA in viral DNA replication." (PMID 37486931, 2023). "This review summarises the role of PCNA in states of inflammation such as malignancy and viral infection, and discusses the currently available data about the role of immune cells within this setting." (PMID 39205238, 2024). "Previous studies indicate that the M protein of SARS-CoV-2 is capable of regulating the translocation of PCNA from the cell nucleus to the cytoplasm, and potentially sustains cell viability via PCNA ubiquitination during viral infection." (PMID 38238762, 2024). "Terminally differentiated Naive.T_PCNA was found to be specifically enriched in both ARDS groups, likely resulting from DNA damage and genomic instability in host cells caused by viral infection." (PMID 38238762, 2024). "The results presented here are consistent with a model whereby PCNA is present at viral replication forks and inhibition of viral infection with PCNA inhibitors blocks key aspects in viral DNA replication and coupled processes." (PMID 37486931, 2023). "The use of PCNA inhibitors that block specific regions of the PCNA protein provide mechanistic understanding of PCNA function during viral infection." (PMID 37486931, 2023). "PCNA has been shown to complement some of the modulatory functions of pE301R during viral infection." (PMID 37772878, 2023). "In a previous study, we demonstrated that PCNA associates with HSV-1 replication forks in a replication-dependent manner and others have shown that PCNA knockdown results in reduced viral infection." (PMID 37486931, 2023). "To further investigate and compare the recovery of C57BL/6 and BALB/c mice from A/H7N9 virus infection, we stained cells for proliferating cell nuclear antigen (PCNA), an indicator of cell proliferation." (PMID 24676272, 2014). "Both of these studies showed that deubiquitination of PCNA was important for downregulating polη recruitment to sites of DNA damage outside the context of infection, but the role of PCNA ubiquitination during viral infection remains to be determined." (PMID 40130902, 2025). "We postulate that the abundance of Naive.T_PCNA could indicate the proliferative potential of T cells in patients after viral infection under post-kidney transplantation immunosuppressive conditions." (PMID 38238762, 2024). "Thus, viral infection can induce Naive.T_PCNA to engage in signaling pathways or ubiquitination, thereby contributing to DNA repair in host cells and facilitating viral replication." (PMID 38238762, 2024). "As PCNA plays a vital role in viral replication, the interactions with p21 in the context of viral infection may emerge as an important tool for allowing sustained viral replication." (PMID 39205238, 2024). "This can be hypothesized as a need for the virus to have PCNA partially translocated from the nucleus to the cytoplasm, and that M is responsible, at least in part, for this translocation in the context of the viral infection." (PMID 35677658, 2022). "PCNA is cytosolic in mature neutrophils and acts in immune response, including to virus infection." (PMID 35677658, 2022). "Moreover, we found that Ad‐Suv39h1 infection increased the PCNA level by more than onefold, while LV‐Suv39h1 shRNA reduced the PCNA level by approximately 50%, as compared with control virus infection (P < .05)." (PMID 31736204, 2020).